PRECSIT (p53 regulated carcinoma associated Stat3 activating long intergenic non-protein coding transcript)
Synonyms: C13orf29; LINC00346; NCRNA00346
Gene: Long non-coding RNA gene on chromosome 13 (110,863,987 to 110,870,476, reverse strand). Ensembl gene ENSG00000255874.
Diseases named in the same sentence as PRECSIT in open-access papers:
PRECSIT is named in the same sentence as 19 diseases in open-access papers, as found by Europe PMC text mining. Sharing a sentence is not in itself a finding about the gene and the disease. The quoted sentences say what the papers report.
cutaneous squamous cell carcinoma (2 papers, 2021). "PRECSIT promotes the progression of cutaneous squamous cell carcinoma via STAT3 signaling." (PMID 35047414, 2021).
tumor (9 papers, 2020 to 2025). "Depletion of PRECSIT inhibits cSCC cell invasion by downregulating STAT3 expression and activation, and production of matrix metalloproteinases (MMPs), MMP-13, MMP-3, MMP-1, and MMP-10, suggesting a tumor-promoting function for PRECSIT." (PMID 32462404, 2020).
PRECSIT also shares sentences with these, for which no sentence is quoted: glioma (10 papers); pancreatic cancer (8); bladder cancer (6); breast carcinoma (6); gastric cancer (5); cancer (4); hepatocellular carcinoma (4); lung adenocarcinoma (3); lung carcinoma (3); non-small cell lung carcinoma (2); atherosclerosis (1); cholangiocarcinoma (1); glioblastoma (1); lymphoma (1); nasopharyngeal carcinoma (1); ovarian carcinoma (1); schizophrenia (1).